VDR (vitamin D receptor)
Diseases named in the same sentence as VDR in open-access papers (continued):
Sharing a sentence is not in itself a finding about the gene and the disease.
chronic kidney disease (55 papers, 2012 to 2025). Impairment of the renal function secondary to chronic kidney damage persisting for three or more months. "Control of iPTH levels with Vitamin D receptor activators- which include Calcitriol, Doxercalciferol, Paricalcitol, and Alfacalcidol-is associated with improved overall survival in chronic kidney disease (CKD) patients." (PMID 41013372, 2025). "This analysis identified specific VDR gene polymorphisms, such as BsmI, FokI, and TaqI, associated with an increased risk of renal diseases, including end-stage renal disease." (PMID 38318147, 2024). "Agreeing with the results of this study, another study concluded that VDR gene polymorphism influences parathyroid function in chronic renal failure." (PMID 37858254, 2023). "The data from meta-analysis study showed that VDR BsmI gene polymorphismwas associated with chronic renal failure in Chinese and Spanish individuals." (PMID 37822821, 2023). "The loss of VDR was associated with reduced expression of E-cadherin and epithelial cell differentiation in chronic kidney disease." (PMID 33671804, 2021). "Altered expression of the VDR is associated with chronic kidney disease and affects mTOR signals and the expression of PD-1 and its ligands." (PMID 33676416, 2021). "We conducted meta-analyses for calcium-sensing receptor gene (CaSR) rs1801725 polymorphism in patients with primary hyperparathyroidism and vitamin D receptor gene (VDR) rs1544410 polymorphism in patients with end-stage renal disease (ESRD)." (PMID 29794776, 2018). "FokI and BsmI polymorphisms of vitamin D receptor (VDR) gene are regarded as reliable markers of disturbed vitamin D signaling pathway which is also associated with end stage renal disease (ESRD)." (PMID 25949827, 2015). "In 2HPT of chronic kidney disease, parathyroid gland hyperplasia, especially in its nodular form, is associated with reduced expression of CaSR and VDR, determining medical therapy resistance." (PMID 23232027, 2012). "The main objective of the study is to study the link between BsmI VDR gene polymorphism and Chronic Kidney Disease (CKD)." (PMID 37822821, 2023). "VDR polymorphisms are associated with occurrence and prognosis of certain diseases, such as chronic kidney disease (CKD), ischemic stroke, and malignant tumors." (PMID 31218132, 2019). "The role of VDR extends into the broader spectrum of chronic kidney disease, where its diminished levels and activity exacerbate conditions like secondary hyperparathyroidism and renal fibrosis." (PMID 38318147, 2024). "Some clinical reports, but not all, have also recently detected improved survival outcomes and additional cardiac/cardiovascular benefits with vitamin D supplementation in patients with heart failure or VDR agonists in patients with chronic renal failure." (PMID 39405125, 2024). "The benefits of vitamin D receptor activators (VDRAs) for patients with chronic kidney disease are well recognized." (PMID 34787531, 2021). "Altered expression of the vitamin D receptor (VDR) is also a prognostic indicator in chronic kidney disease." (PMID 33676416, 2021). "Vitamin D/VDR signaling has been widely reported to be protective in renal diseases like diabetic kidney disease and other chronic kidney diseases." (PMID 31996668, 2020). "Characteristics of studies included in the meta-analysis for the relationship between VDR rs1544410 gene polymorphism and PTH level among patients with the end-stage renal disease." (PMID 29794776, 2018). "Results of meta-analysis for the association between VDR rs1544410 gene polymorphism and PTH level among patients with the end-stage renal disease." (PMID 29794776, 2018). "An increase in creatinine generation and urinary excretion has been described in patients with chronic kidney disease treated with vitamin D receptor activator, paricacitol." (PMID 28231782, 2017).
chronic kidney disease (continued). "Recently, several studies demonstrated that vitamin D receptor (VDR) gene polymorphism is associated with LVM and predicts LVH progression in end-stage renal disease patients." (PMID 25927456, 2015). "On that account, active vitamin D, the ligand of VDR, is used as an adjuvant therapy to control infection, slow down progression of chronic kidney diseases, and cancer chemotherapy." (PMID 26347716, 2015). "Vitamin D receptor activators (VDRAs) have been used in the management of secondary hyperparathyroidism in chronic kidney disease (CKD) for several decades." (PMID 23889806, 2013). "Vitamin D receptor agonists (VDRAs) are commonly prescribed in chronic kidney disease (CKD)." (PMID 35434454, 2022). "The serum 24,25OH2D level was lower in adult patients with chronic kidney disease, which was suggestive of decreases in vitamin D catabolism and VDR activity, and reduced 1,25OH2D production, the level of which better correlated with the serum PTH level than did either the 25OHD or 1,25OH2D level." (PMID 34648586, 2021). "Interestingly, in patients with chronic renal failure, the VDR genetic profile seems to perturb the FGF23 expression and consequently the physiological action of FGF23 mediated by FGF receptor and co-receptor Klotho." (PMID 32899460, 2020). "VDR can form a complex with the p65 subunit of NFκB to produce anti-inflammatory actions and vitamin D supplementation has already been reported to help reducing circulating levels of IL-6 in other populations such as end-stage renal disease patients." (PMID 31179282, 2019). "The results showed that VDR Bsm I gene polymorphism played an important role in estimating LVH risk of MDH patients, and provided theoretical basis for early detection and active prevention of cardiovascular complications and improvement of prognosis of patients with end-stage renal disease." (PMID 35033017, 2022). "It exhibits potent anti-inflammatory effects by activating the vitamin D receptor (VDR), inhibiting NF-κB activity, and suppressing pro-inflammatory cytokines in chronic kidney disease or renal inflammation." (PMID 41184249, 2025). "PTH: Parathyroid hormone; CRF: Chronic renal failure; ESRD: End-stage renal disease; PTH: Parathyroid hormone; SHPT: Secondary hyperparathyroidism; HTRO: High-turnover renal osteodystrophy; iPTH: Intact parathyroid hormone; VDR: Vitamin D receptor." (PMID 39156357, 2024). "Pathological examinations of parathyroid glands in patients with chronic CKD and/or end-stage renal diseases (ESRD) have revealed transformation from diffused to nodular hyperplasia, accompanied by the decrease in CaSR and VDR levels." (PMID 36755240, 2023). "SHPT is a common disorder that occurs in chronic kidney disease (CKD), characterized by significantly reduced expressions of CaSR and vitamin D receptor (VDR), which largely contributes to death and cardiovascular events in CKD patients." (PMID 36755240, 2023). "Consequently the beneficial effects of vitamin D receptor activators in experimental chronic renal failure could be related to downregulation of the renal renin-angiotensin system and in particular to a reduced renin build-up caused by the disruption of the feedback inhibition loop." (PMID 26000281, 2015). "Vitamin D receptor activators reduce albuminuria, and may improve survival in chronic kidney disease (CKD)." (PMID 23889806, 2013). "Furthermore, in a secondary analysis in the paricalcitol and endothelial function in chronic kidney disease (PENNY) trial, we have recently observed that pentosidine modifies the sclerostin response to VDR activation by paricalcitol." (PMID 29362665, 2017). "Hyperphosphatemia, hypocalcemia, low serum vitamin D levels are greatly involved into the physiopathology of SHPT in chronic kidney disease (CKD), in which the down-regulation of parathyroid Vitamin D Receptor (VDR) and Calcium Sensing Receptor (CaSR) represent a critical step." (PMID 25032145, 2014).
chronic kidney disease (continued). "A few human interventions have demonstrated that VDR agonists may reduce proteinuria, but these studies were confined to populations with established chronic kidney disease (CKD), and evaluation of the RAS was not undertaken." (PMID 23971740, 2013).
inflammatory bowel disease (55 papers, 2013 to 2026). A spectrum of small and large bowel inflammatory diseases of unknown etiology. "Vitamin D receptor (VDR) single-nucleotide polymorphisms (SNPs) modulate vitamin D/VDR signaling, a key pathway in inflammatory bowel disease (IBD) pathogenesis." (PMID 40076474, 2025). "Due to its multifaceted regulatory effects on the intestine, the disruption of vitamin D/VDR signaling has been implicated in the pathogenesis of inflammatory bowel diseases (IBD)." (PMID 40076474, 2025). "A vitamin D receptor (VDR) deficiency leads to the dysbiosis of intestinal bacteria and is associated with various diseases, including cancer, infections, and inflammatory bowel disease." (PMID 38248835, 2024). "Unsurprisingly, given this wide range of functions, the VDR and vitamin D deficiency have been linked with the pathogenesis of many diseases, including inflammatory bowel disease (IBD), colorectal cancer, and infections." (PMID 38248835, 2024). "Low 25(OHD)D levels, its metabolisms, and VDR polymorphisms play a central role in Inflammatory Bowel Disease (IBD) pathogenesis, and IBD is a CRC risk factor." (PMID 37371861, 2023). "The role of VDR in intestinal epithelial cells has been described by several studies with a focus on inflammatory bowel diseases (IBDs) as epidemiological data indicate an association between vitamin D3 deficiency and increased risk of IBD." (PMID 36341397, 2022). "The vitamin D receptor (VDR) is critical in regulating intestinal homeostasis and emerging evidence demonstrates that VDR deficiency is a critical factor in inflammatory bowel disease pathology." (PMID 36341397, 2022). "In particular, vitamin D and VDR deficiency exacerbates experimental inflammatory bowel disease (IBD)." (PMID 29684027, 2018). "In line with the described in vitro observations, vitamin D receptor (VDR) knockout (KO) mice are more susceptible to Th1-mediated autoimmunity, for instance, to multiple sclerosis and inflammatory bowel disease." (PMID 26035244, 2015). "VDR depletion in mice increases inflammation and predisposition to inflammatory bowel disease or enhances its severity, while vitamin D supplementation could improve the symptoms of patients with inflammatory bowel disease." (PMID 36145154, 2022). "Clinical trials have shown that VD deficiency and low VDR level are highly prevalent in patients with inflammatory bowel diseases who are vulnerable to GI syndrome, suggesting that GI syndrome may be associated with low VD/VDR level." (PMID 34578802, 2021). "In this stringent test, these replicated VDR-BVs were significantly (q < 0.1) and substantially (>2-fold) enriched in genomic intervals associated with autoimmune and other diseases, including inflammatory bowel disease, Crohn’s disease and rheumatoid arthritis." (PMID 28335003, 2017). "Genetic studies have identified susceptibility genes for CD, among which, the human VDR gene, located on chromosome 12q13.11 is situated within one of the candidate regions for inflammatory bowel disease (IBD) susceptibility." (PMID 39458479, 2024). "Vitamin D receptor (VDR) deficiency contributes to the development of experimental inflammatory bowel disease (IBD) in several different models." (PMID 24502291, 2014). "When the vitamin D signaling pathway is disrupted, the development of inflammatory bowel disease demonstrates the importance of vitamin D/VDR in maintaining intestinal homeostasis." (PMID 41450574, 2025). "Studies in intestinal epithelial cells demonstrate that diminished VDR expression is associated with decreased ATG16L1 levels and compromised autophagy, consequently elevating the risk of inflammatory bowel disease." (PMID 40728969, 2025). "Emerging evidence highlights a bidirectional regulatory interplay between VD/VDR signaling and gut microbiome dynamics, particularly in inflammatory bowel disease (IBD)." (PMID 40728969, 2025).
inflammatory bowel disease (continued). "With regards to inflammatory bowel diseases (IBDs) such as ulcerative colitis and Crohn's disease, the VDR protein plays a crucial regulatory role, influencing immune modulation, epithelial barrier integrity, and cellular proliferation in the intestine." (PMID 38334807, 2024). "The VDR pathway is a promising target for the prevention of high-fat diet-induced inflammatory bowel disease, according to O’Mahony, C.." (PMID 37446182, 2023). "The VDR signaling pathway performs an important function in the regulation of inflammatory responses—especially in inflammatory bowel disease—by transmitting signals of bile acids via VDR within the adaptive immune system." (PMID 36359206, 2022). "The vitamin D/VDR pathway is known to play a role in chronic inflammation of the gastrointestinal tract, such as inflammatory bowel disease, by regulating junctional proteins and inflammatory cytokines." (PMID 34072725, 2021). "Vitamin D and the vitamin D receptor (VDR) is important in immunological regulation in disease such as inflammatory bowel diseases (IBD) and human immunodeficiency virus infection by modulating the function of monocytes/macrophages during infection." (PMID 33509250, 2021). "We performed a search of the PubMed database including several interrelated queries: “vitamin D”, “vitamin D receptor”, “inflammatory bowel diseases”, “ulcerative colitis”, “Crohn’s disease”, “microbiota”, “spondyloarthritis”, and “arthritis”." (PMID 33671090, 2021). "The VDR regulates the intestinal proliferation, barrier function, and immunity, and plays a protective role in inflammatory bowel diseases." (PMID 29986424, 2018). "For example, IL10 expression can be induced using AHR agonists as a protective mechanism in inflammatory bowel disease, or repressed by an endogenous VDR agonist (calcitriol) during pregnancy to enhance responses to microbial infections." (PMID 30184180, 2018). "Loss of ATG16L1 or VDR expression impairs autophagy, resulting in cellular dysfunction, and has been associated with intestinal dysbiosis and inflammatory diseases, including inflammatory bowel disease (IBD)." (PMID 30828578, 2018). "Chronic mucosal inflammation and TNFα-induced down-regulation of gut epithelial VDR can be observed in cases of inflammatory bowel disease." (PMID 29684027, 2018). "There is a growing body of evidence concerning the therapeutic role of vitamin D/synthetic vitamin D receptor agonists in clinical and experimental models of inflammatory bowel disease far beyond the role of calcium homeostasis and bone metabolism." (PMID 26000293, 2015). "Interestingly, there is a crucial correlation among autophagy, VDR, and the gut microbiome, which affects intestinal homeostasis and plays a significant role in the pathophysiology of inflammatory bowel disease." (PMID 36233580, 2022). "Future research is needed to enhance our understanding of the complex interplay of nuclear receptors and probiotics, specifically VDR’s contribution to probiotic-induced anti-inflammation and its potential role in inflammatory conditions such as inflammatory bowel diseases." (PMID 33396898, 2020). "Immune activity in genetic ASD resembles immune activity in inflammatory bowel disease yet the influence of VDR in ASD immune activity is lacking." (PMID 32634371, 2020).
Hypocalcemia (54 papers, 2010 to 2025). An abnormally decreased calcium concentration in the blood. "The active VD metabolite, 1,25-dihydroxyvitamin D (1,25-(OH)2D), binds to the VDR in the intestine to facilitate active Ca transport, and VD deficiency reduces intestinal absorption of Ca and P, which in turn leads to hypocalcemia and hypophosphatemia." (PMID 38410638, 2024). "It is well known that VDR-ablated mice on a normal diet develop severe secondary hyperparathyroidism (sHPT) due to a loss of VDR function in the small intestine, leading to a calcium absorption defect and subsequent hypocalcemia." (PMID 30273386, 2018). "Aberrant growth plate, however, appears before the onset of hypocalcemia in VDR-deficient mice, supporting a defined role for 1,25(OH)2D3 in the process of endochondral bone formation." (PMID 21695192, 2011). "VDR genotypes increase the risk for low BMD and osteoporotic fractures and VDR knock-out mice develop a low bone mass phenotype with hypocalcemia, hypophosphatemia, and elevated 1,25(OH)2D3 levels." (PMID 20961463, 2010). "Interestingly, in mice and humans, inactivating mutations in CYP27B1 and VDR result in hypocalcemia, hypophosphatemia, secondary hyperparathyroidism and short, deformed bones with dysmorphic growth plates." (PMID 39164247, 2024). "Intestinal VDR KO might lead to hypocalcemia and weight loss unless mice were reared and maintained on a “rescue” diet high in calcium." (PMID 37074210, 2023). "However, a possible explanation may be that only more severe hypocalcaemia may impair cardiac function after MI in VDR deficient mice." (PMID 30273386, 2018). "Previous studies in global VDR knockout mice demonstrated abnormalities in bone mineral homeostasis and slight hypocalcemia, accompanied by compensatory increases in circulating 1,25(OH)2D3." (PMID 41292920, 2025). "Another possible explanation is that 1,25 (OH)2D3 activity in the parathyroid glands of kidney transplanted rats is improved by cessation of hypocalcaemia, despite persistently low VDR expression." (PMID 36267284, 2022). "When VDR null animals are placed on a normal diet (ND), significant phenotypic effects are seen, including hypocalcemia and hyperparathyroidism." (PMID 35662320, 2022). "To avoid the confounding effects of VDR‐mediated developmental and hypocalcaemia‐related dysregulation inherent to germline genetic manipulation, we modified VDR expression in post‐natal skeletal muscle." (PMID 33258480, 2021). "To further explore the interaction between VDR signalling and hypocalcaemia for heart function post-MI, we performed an additional experiment with WT and VDR deficient mice on normal and rescue diet." (PMID 30273386, 2018). "In accordance with our earlier reports, the rescue diet largely protected 3-month-old VDR mutants against the development of hypocalcemia and hypophosphatemia." (PMID 30273386, 2018). "The rescue diet prevents hypocalcemia and sHPT in global VDR mutants by stimulating paracellular uptake of calcium and phosphate in the gut." (PMID 30273386, 2018). "Although we also observed hypocalcemia, we adjusted hypocalcemia by increasing calcium-based phosphate binder and/or vitamin D receptor activators." (PMID 28912972, 2017). "The mechanisms by which these conditions develop are mainly related to concomitant hypocalcemia; however, some direct effects via VDR on endothelial function may also be involved." (PMID 40431432, 2025). "However, the interpretation of the muscle phenotype in VDR-deficient mice requires careful attention because the congenital and systemic deletion of VDR affects the development and growth of mice, and the onset of hypocalcemia and cirrhosis has been reported." (PMID 36774476, 2023). "Evocalcet with concomitant vitamin D receptor activator demonstrated benefits such that more patients achieved the corrected calcium target and exhibited decreased fibroblast growth factor-23 synthesis; the incidence of hypocalcemia also decreased." (PMID 35176038, 2022).